EZH2 (enhancer of zeste 2 polycomb repressive complex 2 subunit)
Diseases named in the same sentence as EZH2 in open-access papers (continued):
Sharing a sentence is not in itself a finding about the gene and the disease.
lymphoma (297 papers, 2004 to 2026). A malignant (clonal) proliferation of B- lymphocytes or T- lymphocytes which involves the lymph nodes, bone marrow and/or extranodal sites. "Ongoing clinical trials are exploring the potential of small‐molecule inhibitors for HMTs such as EZH2, which is implicated in various cancers, including lymphomas and sarcomas." (PMID 40181550, 2026). "Gain-of-function mutations in EZH2 occur in approximately 20–25% of FL cases and were among the first epigenetic alterations identified as critical drivers in the early stages of this lymphoma." (PMID 40943058, 2025). "These methods identified a novel feature of EZH2 mutation in increasing epigenetic heterogeneity in diverse lymphoma models." (PMID 40504770, 2025). "Common GOF mutations include EZH2 Y646, A682, and A692, with the EZH2 Y646 mutation in particular being frequently reported in lymphomas such as diffuse large B-cell lymphoma and follicular lymphoma (left)." (PMID 40562788, 2025). "Focusing then on lymphoma-associated EZH2 mutations, we show that Ezh2Y641F induces aberrant H3K27 methylation patterns even without wild-type Ezh2, which are alleviated by partial PRC2 inhibition." (PMID 38658543, 2024). "Cells carrying EZH2 mutations found in lymphoma show a specific transcriptional response to PRC2 inhibition." (PMID 38658543, 2024). "Phase II trials with the drug Tazemetostat have demonstrated favorable results in lymphoma patients carrying EZH2 mutations, achieving an impressive 69% objective response rate, while those with wild‐type EZH2 just saw 35% of response rate." (PMID 39118438, 2024). "For example, it has been recently highlighted that mutations in the SET domain of EZH2 in human lymphomas result in aberrant activation of PcD and elevation of H3K27me3." (PMID 39769907, 2024). "Disease-related heterozygous point mutations within the SET-domain of EZH2 mainly found in lymphomas and myeloid leukemias, alter the substrate specificity of EZH2 to generate different methylation states of H3K27 which promote oncogenic progression." (PMID 38242973, 2024). "Tazemetostat and GSK126 are both highly selective for wild-type and lymphoma-associated EZH2 mutants." (PMID 39768352, 2024). "The EZH2 inhibitor tazemetostat has been approved for EZH2-mutant lymphoma and INI1-deficient soft tissue sarcoma, signaling is a major breakthrough in epigenetics-based medicine." (PMID 37394582, 2023). "First, they are associated with MHC class I and MHC class II loss in mouse models and human lymphomas, and pharmacological inhibition of EZH2 enhances MHC class I expression in GCB-DLBCL cell lines." (PMID 38022603, 2023). "In lymphoma cells with EZH2 gain-of-function mutations, the re-localization of MLL-MEN1 complex drives oncogenic gene expression and results in a hypersensitivity to pharmacologic inhibition of MEN1." (PMID 37460547, 2023). "Our mechanistic investigation into the essentiality of the MLL–MEN1 complex in EZH2-mutated lymphomas provides one example of cancer-associated mutations in chromatin enzymes that creates a synthetic dependency on its interacting trans-regulatory pathway." (PMID 37460547, 2023). "After bivariate analysis, only the presence of double-hit lymphoma (p = 0.04) and EZH2 mutations either on tumor analysis (0.047) or ctDNA (0.021) were factors associated with relapse." (PMID 36230571, 2022). "After bivariate analysis, only the presence of double-hit lymphoma (p = 0.04) or EZH2 mutations were associated with relapse." (PMID 36230571, 2022). "For example, FL and DLBCL patients carrying EZH2 mutations identified in lymphoma tissue or ctDNA show a better response to the EZH2 inhibitor tazemetostat than patients with wildtype EZH2." (PMID 35701522, 2022). "Although loss- and gain-of-function EZH2 mutations have been documented in lymphomas, myeloid malignancies, leukemias, and solid tumors, only truncating mutations in the H3K36 methyltransferase SETD2 have been reported in pediatric high-grade gliomas (pHGG)." (PMID 35395831, 2022).
lymphoma (continued). "Knock-in of the GoF mutation EZH2-Y641F in mouse led to the occurrence of spontaneous lymphoma, demonstrating its onco-driver activity." (PMID 35169119, 2022). "EZH2 point mutations in tyrosine 641 (Y641F, Y641N, Y641S, and Y641H) have been identified in 8–24% of lymphomas, whereas mutations A677G and A687V have been identified in non-Hodgkin’s lymphomas." (PMID 34298959, 2021). "Inhibition of H3K27 trimethylation (H3K27Me3) leads to selective cell killing of human lymphoma cell lines bearing EZH2 catalytic domain point mutations." (PMID 34721544, 2021). "The frequent tyrosine 641 (Y641) mutation of EZH2 in lymphomas is a gain-of-function mutation that enhances tri-methylation of H3K27 in concert with EZH2WT that performs the H3K27 mono-methylation, eventually shutting down key B-cell genes." (PMID 35008680, 2021). "A gain-of-function EZH2 mutation characterized by an aberrant H3K27me3 occupancy blocked B cell development and was found in several lymphomas, whereas a loss-of-function of EZH2 is common in myelodysplastic syndromes." (PMID 33401659, 2021). "EZH2 mutations have been frequently reported in certain cancer types, including leukemia, lymphoma, and melanoma." (PMID 34065631, 2021). "EZH2 inhibitors are mainly studied in lymphomas and solid tumors in which gain-of-function mutations of EZH2 occur." (PMID 33917538, 2021). "EZH2 is activated by mutations (gain-of-function) in lymphoma, and EZH2 overexpression is associated with aggressiveness and worse clinical outcome in several solid tumors, including prostate, breast, bladder, and endometrial cancers, and melanoma." (PMID 33879235, 2021). "Monoallelic mutation results in the expression of wild-type and mutated EZH2, which causes the dysregulation of transcriptome in lymphoma cells according to the accumulation of H3K27me3." (PMID 33163485, 2020). "This mutation mediates the gain-of-function of EZH2 enzymatic activity, therefore, promotes H3K27me3 and suppress gene expressions more strongly in lymphoma." (PMID 32723346, 2020). "Lymphoma-associated mutations affecting Polycomb protein EZH2 represent gain-of-function alterations, which enhance EZH2 methyltransferase activity leading to increased H3K27me3 and repression of transcription." (PMID 33260693, 2020). "Gain-of-function mutations of EZH2 are mainly detected in diffuse large B cell lymphoma and follicular lymphoma among all categories of lymphomas and lymphoid leukaemia." (PMID 35582230, 2020). "Histone methyltransferase EZH2 is the catalytic subunit of PRC2, and the tyrosine 641 (Y641) of EZH2 is the most frequently mutated residue, up to 22% of germinal center-derived lymphomas and 24% of FL acquiring mutations at this site." (PMID 32850364, 2020). "Complicating the story, both gain- and loss-of-function mutations in EZH2 are frequent in various types of cancer including lymphomas, melanoma, and myelodysplastic lymphoma (MDS)." (PMID 33003334, 2020). "Previously, several lymphoma-specific hotspot mutations, including EZH2, were shown to be detectable from plasma derived ctDNA of FL and DLBCL patients." (PMID 32668764, 2020). "In lymphomas, EZH2 can be activated by different mutations, and the use of EZH2 inhibitors allow the selective killing of tumor cells carrying these mutations." (PMID 32708698, 2020). "The gain-of-function EZH2 mutations present in several lymphomas, is responsible for aberrant histone H3K27me3 resulting the blockage of B-cell development." (PMID 32257110, 2020). "Multiple aberrations in histone PTMs have been observed in leukemias and lymphomas, such as EZH2 mutations altering H3 K27 methylation, DOT1L dysregulation of H3 K79 methylation with MLL translocations, and KMT2D mutations affecting H3 K4 methylation." (PMID 33104722, 2020). "Activating mutations in EZH2 are frequently found in lymphoma and are considered disease drivers that display a target for pharmacological inhibition." (PMID 33371192, 2020).
lymphoma (continued). "Another EZH2 inhibitor, GSK126, is reported to significantly impair the growth of lymphoma with EZH2 gain-of-function mutations in vivo." (PMID 32906688, 2020). "Inhibition of EZH2 has been proposed as a therapeutic strategy to induce apoptotic cell death in cancers with a frequent gain of function mutation or over-expression of EZH2 such as melanoma, ovarian cancer, and lymphoma." (PMID 33180829, 2020). "Dysregulation of H3K27me3 is frequently observed in many types of cancers, and overexpression of EZh2 or mutations in the SET domain of EZH2 have been reported in lymphomas, causing an increase of H3K27me3." (PMID 30806885, 2019). "Similar effects have been described as a consequence of the A677G mutation in EZH2, which has been characterized in multiple human lymphoma cell lines." (PMID 31681423, 2019). "EZH2 inhibitors, now in clinical trial, are showing promising anticancer effect in lymphoma, as well as in solid tumors carrying mutations in the SWI/SNF chromatin remodeling complex." (PMID 31817960, 2019). "Correlation between the lymphoma type, EZH2 mutation status, MYC, BCL2 and BCL6 rearrangements and DZNep sensitivity." (PMID 31419226, 2019). "Owing to changes in substrate-binding modality, lymphoma associated EZH2 SET domain mutants have an enhanced ability to convert H3K27me2 to me3." (PMID 31123059, 2019). "Among all categories of lymphomas and lymphoid leukemias, gain-of-function somatic mutations of EZH2 were mostly detected in GC-derived diffuse large B cell lymphoma (DLBCL) and follicular lymphoma (FL)." (PMID 31752930, 2019). "Several direct EZH2 inhibitors have been developed and their efficacy for the induction of apoptosis in lymphoma cell lines was demonstrated, however, most of these direct inhibitors induce apoptosis preferably in cell lines bearing EZH2 point mutations." (PMID 31419226, 2019). "EZH2 gain-of-function mutations were previously reported in lymphoma, and the probability of EZH2 mutation in melanoma was recently reported to be about 2%." (PMID 30984620, 2019). "Overexpression and gain-of-function mutations in EZH2 are regarded as oncogenic drivers in lymphoma and other malignancies due to the silencing of tumor suppressors and differentiation genes." (PMID 31419226, 2019). "A detailed study reported that EPZ005687, a SAM-competitive inhibitor, can inhibit H3K27 methylation mediated by the EZH2 mutants Y641 and A677, and has also been shown to selectively kill lymphoma cells that are heterozygous for one of these EZH2 mutations." (PMID 30103412, 2018). "The second anticancer drug is EPZ005687, it also targets Y641 and A677 mutated EZH2 found in nonHodgkin lymphoma where it reduces H3K27 methylation in lymphoma cells." (PMID 30344952, 2018). "Recurrent somatic mutations of EZH2 have been identified in subtypes of lymphoma, and EZH2 gain-of-function mutations alter substrate specificity for promoting hypertrimethylation of H3K27." (PMID 29930752, 2018). "EZH2 mutation (Y641F) globally increased the abundance of H3K27me3 in lymphoma and melanoma, but also caused a widespread redistribution of this repressive mark, including a loss of H3K27me3 that was associated with increased transcription at many loci." (PMID 29556394, 2018). "EZH2 is a druggable target in different cancers, and commercial catalytic EZH2i, such as EPZ005687 and GSK2816126, are used in lymphoma with EZH2-activating mutations and also in solid tumors." (PMID 28978137, 2017). "We first evaluated the performance of our hybridization capture-based method on serial dilutions of a cell line (DB) genomic DNA carrying a mutation (EZH2 p.Y641N) that was covered by our lymphoma-specific capture gene panel." (PMID 28874686, 2017). "Pharmacologic inhibitors of EZH2 are in clinical trials for diseases where PRC2/EZH2 hyperfunction is clearly linked to malignant transformation (such as lymphomas with activating EZH2 mutations or INI1-negative solid tumors)." (PMID 28232907, 2017).
lymphoma (continued). "Two other EZH2 inhibitors, GSK126 and EPZ005687, have shown preferential effectiveness in suppressing the growth of lymphoma-associated mutants of EZH2 in comparison to those with wild-type EZH2." (PMID 27329599, 2016). "Lately, hyper-activated mutation of histone methyltransferase EZH2 has been identified in the pathogenesis lymphoma." (PMID 26848523, 2016). "Lymphomas with an activating mutation in the catalytic SET domain of EZH2 are strongly affected by treatment with the EZH2 inhibitor GSK126 and clinical trials with EZH2 inhibitors are currently ongoing." (PMID 27634879, 2016). "EZH2 is implicated in a number of malignancies and importantly, is directly involved in development of various lymphomas including diffuse large B cell lymphoma (DLBCL) derived from germinal center B cells." (PMID 27167731, 2016). "EZH2 is mutated in a variety of tumors including lymphomas and targeting of EZH2 protein with specific inhibitors show promising results in preclinical studies and early clinical trials." (PMID 27993143, 2016). "Work using RNAi knockdown and small molecule inhibitors of EZH2 has shown that EZH2 is required for the proliferation of EZH2 mutant lymphoma cells, SMARCB1-deficient MRT cells and cells from other cancer types." (PMID 26578851, 2015). "The EZH2 gain-of-function (GOF) mutations first identified in lymphomas have recently been reported in melanoma (~2%) but remain uncharacterized." (PMID 25671303, 2015). "Another heterozygous mutation of EZH2 at alanine 677 to glycine (A677G) is also identified in lymphoma cell lines and primary lymphoma samples with frequency less than 2-3%." (PMID 25520914, 2014). "Recent evidence demonstrated that small molecule inhibition of EZH2 significantly reduced growth of germinal center-derived DLBCL cells, and conditional expression of an EZH2 mutant lymphoma allele was shown to drive lymphomagenesis." (PMID 25255445, 2014). "Overexpression/amplification or mutation of EZH2 have been found in a wide range of cancer types, including breast, prostate, lung, liver, colon, ovarian, bladder, glioblastoma and lymphoma." (PMID 25520914, 2014). "For example, if a lymphoma specimen is shown to have EZH2 mutation and pSTAT3 expression, experimental treatment with an EZH2 inhibitor or a JAK2 inhibitor can be offered, but which treatment should be considered first?" (PMID 24870942, 2014). "These compounds are selective for EZH2 over other SET domain methyltransferases, are able to inhibit catalytic activity of both wild-type and lymphoma-associated mutants of EZH2 and reduce the cellular level of H3K27me3." (PMID 24367611, 2013). "The activating somatic mutation Y641 of EZH2 leads to high H3K27 trimethylation in lymphomas, and high levels of H3K27me3 consequent to EZH2 hyperactivity have been reported in hepatocellular carcinoma and esophageal squamous cell carcinoma." (PMID 23110793, 2012). "In contrast to the mutations seen in lymphoma, EZH2 mutations in myeloid neoplasms in SET domain are mostly nonsense and stop codon mutations, and thus are deficient in their histone methyltransferase activity." (PMID 22187039, 2012). "Curiously, a recurrent mono-allelic activating mutation has been identified in EZH2 at tyrosine 641 in patients with lymphomas while a series of apparent loss-of-function mutations have been found in patients with MDS and primary myelofibrosis." (PMID 21811504, 2012). "EZH2 overexpression is commonly associated with poor prognosis in a variety of tumor types including carcinomas, lymphomas and soft tissue sarcomas." (PMID 23110793, 2012). "We and others have recently demonstrated that miR-26a possessed the tumor-suppressive functions by directly targeting the EZH2 oncogene in cancers e.g. nasopharyngeal carcinoma, lymphoma and HBV-associated HCC cells." (PMID 21829663, 2011). "To determine the function of lymphoma-associated EZH2 mutations in a cellular context, we PCR cloned the EZH2 coding sequence from human bone marrow cDNA." (PMID 22194861, 2011).